PHGDH (phosphoglycerate dehydrogenase)
Diseases named in the same sentence as PHGDH in open-access papers (continued):
Sharing a sentence is not in itself a finding about the gene and the disease.
cancer (continued). "It is a situation that has led some scholars such as Luo to suggest that purported “addiction” to PHGDH observed in cancer cells might actually represent a set of distinct, albeit variable, “metabolic addictions” with some cells (or cell lines) requiring serine while others require aKG." (PMID 25574168, 2014). "Based on these results, PHGDH may be an ideal drug target for cancer therapy." (PMID 23229761, 2013). "The interplay between PHGDH and nicotinamide adenine dinucleotide (NAD+) metabolism is a pivotal axis in cellular adaptation, with profound implications in cancer and immunity." (PMID 41486146, 2026). "Resolution: Couple PHGDH inhibitors with differentiation agents (e.g., retinoic acid) and monitor SAM levels to disrupt cancer stemness." (PMID 41486146, 2026). "Data from the human Cancer Cell Line Encyclopedia (CCLE) demonstrated differential expression of these genes across cell lines, with high expression of PHGDH, PSAT1, SLC1A5 and SLC38A2, and low expression of SLC38A4 and SLC7A10." (PMID 40660426, 2025). "3-phosphoglycerate dehydrogenase (PHGDH), a catalyst in the serine synthesis pathway, was identified as a major determinant of BM for NSCLC and other cancer types." (PMID 39998776, 2025). "PHGDH, the first rate-limiting enzyme in the SSP, is high-expressed in various metabolic disorders, including cancer and glucose metabolism, to produce serine supplying one-carbon unit for the synthesis of nucleotide to meet the need of tumor cell growth." (PMID 39861441, 2025). "Critically, PHGDH, PSAT1, PSPH, SLC1A4, SLC1A5 and SLC38A2 show robust co‐expression patterns in both TCGA tumour samples and CCLE cancer cell lines, suggesting coregulated functionality." (PMID 40660426, 2025). "JOSD2 depletion enhances the ubiquitination degradation of PHGDH, thereby inhibiting HCC proliferation and cancer stem cell (CSC) phenotype with prognostic and functional significance." (PMID 40598535, 2025). "We further found that the expression of PHGDH varies across TCGA cancers (Fig. EV2), indicating downregulating SSP is cancer type dependent." (PMID 40475404, 2025). "CBR-5884, a selective small-molecule inhibitor targeting phosphoglycerate dehydrogenase (PHGDH), effectively impedes the de novo synthesis of serine within cancer cells." (PMID 38733440, 2024). "Phosphoglycerate dehydrogenase (PHGDH) is a dehydrogenating metabolizing enzyme involved in the serine synthesis pathway (SSP), which has been found to play a central role in cancer growth and proliferation." (PMID 38736872, 2024). "Copy number gain or overexpression of PHGDH and PSPH are found in several cancer types, including ER-negative breast cancers, melanoma, lung adenocarcinoma, T-cell ALL and osteosarcoma." (PMID 38698089, 2024). "High expression of serine metabolism-related enzymes, such as phosphoglycerate dehydrogenase (PHGDH) and phosphoserine phosphatase (PSPH), is observed in aggressive cancer subtypes." (PMID 38785550, 2024). "Phosphoglycerate dehydrogenase (PHGDH) has emerged as a crucial factor in macromolecule synthesis, neutralizing oxidative stress, and regulating methylation reactions in cancer cells, lymphocytes, and endothelial cells." (PMID 38409249, 2024). "For instance, KIF15 interacted with phosphoglycerate dehydrogenase (PHGDH) and stabilized it, thus promoting cancer stem cell phenotype and malignancy via PHGDH-mediated reactive oxygen species imbalance in HCC." (PMID 37957153, 2023). "The newer generation of drugs selectively targeting key metabolic enzymes in SGOC metabolism, such as PHGDH, MTHFDs, DHFR, TYMS, GART and CBS, will provide a new strategy for cancer treatment in the future." (PMID 37147729, 2023). "This comes with a further cost to cancer cells: when de novo serine synthesis is inhibited by a pharmacological inhibitor of the first enzyme of the SSP, PHGDH, serine utilization by SHMT2 is reduced." (PMID 37949226, 2023).
cancer (continued). "More importantly, in line with our findings in a mouse model and human cancer cell lines, neutrophil infiltration in human HCC samples positively correlates with the nuclear PHGDH signal." (PMID 37078828, 2023). "PHGDH is the major rate-limiting enzyme in the first step of the SGOC pathway, which is abnormal in various diseases, especially in cancers." (PMID 37147729, 2023). "Some novel therapeutic agents targeting serine metabolic pathways (e.g., PHGDH, PSAT1, and PSPH) in cancer seem to have great potential." (PMID 37187454, 2023). "We also revealed six oncogenes that have been validated to be related to the poor prognosis of patients with cancer: CTSE, CALM1, PHGDH, IL9R, and CD96." (PMID 35433683, 2022). "The upregulation of the first rate-limiting enzyme of the SSP, 3-phosphoglycerate dehydrogenase (PHGDH), has been identified in a large subset of cancers." (PMID 35186770, 2022). "Overexpression of PHGDH was first described in triple-negative breast cancer (TNBC) and has drawn considerable attention in the field of cancer research ever since." (PMID 36291844, 2022). "has shown that over-expression of KIF15 promoted the cancer stem cell (CSC) phenotype and malignancy through phosphoglycerate dehydrogenase (PHGDH)-regulated intracellular reactive oxygen species disorders in HCC." (PMID 35359374, 2022). "Given the dependency of numerous cancers on the SBP and PHGDH expression, PHGDH inhibition is also a promising therapeutic vulnerability." (PMID 36276057, 2022). "Albeit to a lesser extent, it can be produced by enzyme D-3-phosphoglycerate dehydrogenase (PHGDH), the first enzyme in the serine biosynthetic pathway, which is genomically amplified in various cancer types." (PMID 34203535, 2021). "Here we show that inhibition of PHGDH, the first step in the SSP, cooperates with serine and glycine depletion to inhibit one-carbon metabolism and cancer growth." (PMID 33446657, 2021). "Most tumor specimens showed higher expression of PHGDH, USP7, and CTGF compared with the matched para-carcinoma tissues." (PMID 34055773, 2021). "Recently, numerous reports highlighted the crucial role of the serine synthetic pathway, and particularly of the phosphoglycerate dehydrogenase (PHGDH), the first enzyme of the pathway, to sustain cancer progression." (PMID 31979167, 2020). "Although PHGDH, PSAT1 and PSPH have been identified as prognostic biomarkers of a variety of cancers, including GBMs, if they can serve as potential biomarkers of LGGs has not been extensively studied before." (PMID 31861486, 2019). "From a literature review, overexpression of PHGDH, PSPH and PSAT1 proteins are known to lead to poor outcomes in various cancers." (PMID 31861486, 2019). "Here, we show that in monolayer cancer cell-line cultures, the expression of the five metabolic enzymes of serine-glycine synthesis (SGS), including its rate-limiting enzyme, phosphoglycerate dehydrogenase (PHGDH), displays stochastic cell-to-cell variation." (PMID 29925909, 2018). "Altogether, these findings unveil a previously unexplored role of PHGDH in the regulation of self-renewal and stemness factors (KLF4, Oct4, Nanog, Sox-2, and Lin28B) in cancer stem-like cells." (PMID 30250195, 2018). "The expression of PHGDH (p < 0.001), PSAT1 (p = 0.001), PSPH (p = 0.008), tumoral SHMT1 (p < 0.001), and stromal SHMT1 (p < 0.001) was different according to cancer subtype." (PMID 27277113, 2016). "Application of the integrative modelling to cancer genes revealed a major role for MAT enzymes (MAT2B and MAT2A), as well as PHGDH and GATM—enzymes involved in serine and glycine metabolism, respectively." (PMID 27966532, 2016). "Several potential candidates that are overexpressed in certain cancer types include PKM2, GLUT1, HK2, PHGDH and LDH-A." (PMID 27385092, 2016).
cancer (continued). "Phosphoglycerate dehydrogenase PHGDH serves to divert glycolytic carbon into serine and glycine metabolism in some cancer cells to supply the increased biosynthetic needs of transformed phenotype." (PMID 24743024, 2014). "In addition, PHGDH and PSAT expression levels are elevated in human intestinal tumors with deficiency of Protein kinase C(PKC)ζ, which promotes the plasticity necessary for cancer cells to use glutamine through the serine biosynthesis pathway in the absence of glucose." (PMID 24318446, 2013). "This work highlighted the major involvement of the serine biosynthetic cascade controlled by 3-phosphoglycerate dehydrogenase (PHGDH), which was recently shown to be significantly relevant in cancer." (PMID 24062985, 2013). "Cancer-specific contexts, dictated by oncogenic drivers (e.g., MYC, EWS-FLI1), tumor suppressors (e.g., Parkin), and microenvironmental insults, dynamically tune PHGDH expression and activity." (PMID 41486146, 2026). "In summary, this detailed analysis not only underscores the significance of SMGs, particularly PHGDH and SLC1A5, in cancer biology but also lays the groundwork for unravelling the complex molecular mechanisms through which serine influences the tumour microenvironment and immune architecture." (PMID 40660426, 2025). "PHGDH, the first and rate-limiting enzyme of SSP, has been reported to be overexpressed in multiple cancers, such as breast cancer, melanoma, renal cell carcinoma and non-small cell lung cancer, where it contributes to aggressive phenotypes and resistance to therapy." (PMID 40475404, 2025). "Under hypoxic conditions, serine synthesis is driven by three enzymes—phosphoglycerate dehydrogenase (PHGDH), phosphoserine aminotransferase (PSAT), and phosphoserine phosphatase (PSPH)—whose expression is induced by HIF-1α and is crucial for cancer cell proliferation." (PMID 40813760, 2025). "PHGDH and PSAT1 are up-regulated in ERneg BC, and both have important roles in cancer development." (PMID 40117373, 2025). "The finding that some cancer cells exhibit a more oxidized NAD+/NADH ratio upon serine starvation is surprising, particularly when increased serine synthesis will result in a higher demand for NAD+ to support increased flux through GAPDH and PHGDH." (PMID 40654753, 2025). "Inhibitors targeting PHGDH, such as NCT-503, have shown potential in cancer therapy." (PMID 40989165, 2025). "Recently, a non-metabolic function of PHGDH has been highlighted in cancers, often dependent on its nuclear localization." (PMID 40640948, 2025). "Moreover, in glioma cells, PHGDH also interacts and stabilizes FOXM1, thereby inducing the expression of genes involved in cancer progression." (PMID 40640948, 2025). "Furthermore, both entities displayed a shared regulation of genes, including MYC, PHGDH, FBXO2 and BRDT, which promote cancer progression according to previous studies." (PMID 38725048, 2024). "Increasing the ubiquitination degradation of PHGDH may effectively suppress the growth of HCC cells and the characteristics of cancer stem cells." (PMID 38541004, 2024). "Research has shown that PHGDH is excessively produced in HCC cells, and suppressing PHGDH expression may substantially impact cancer cell proliferation, migration, and invasion." (PMID 38541004, 2024). "Research on the proteins that regulate PHGDH is ongoing, and it can be seen that PHGDH does not act alone in cancer but has factors through which partnerships are formed." (PMID 38945960, 2024). "Studies have shown that in the absence of amino acids, cancer cells induce the expression of PHGDH, PSAT1, and PSPH in a GCN2-ATF4-dependent manner to produce sufficient amino acids." (PMID 37147729, 2023). "Thus, our data uncovers eIF3f is a critical cancer biomarker regulating SGOC pathway and provides novel insights into targeting eIF3f‐PHGDH axis as potential CRC treatment strategies." (PMID 37544925, 2023).
cancer (continued). "Given the important role of PHGDH and PKM2 in cancer cell proliferation, PHGDH could also promote tumorigenesis by interacting and regulating the stability and activity of PKM2." (PMID 36899022, 2023). "The serine synthesis pathway is catalysed by several enzymes, such as PHGDH, SHMT1/2, and MTHFD1/2, and their suppression may decrease cancer cell growth and survival." (PMID 37664062, 2023). "These inhibitors showed effective anti-cancer activity against PHGDH-dependent cancers but not against PHGDH-non-dependent cancers." (PMID 37664062, 2023). "PHGDH may co‐express and physically interact with ASNS, a gene that catalyzes glutamine to asparagine, and other cancer‐related genes." (PMID 37387559, 2023). "For example, PKCζ blocks SSP activation by suppressing PHGDH and PSAT1 activity, and PKCζ phosphorylates PHGDH at T57/T78 to inhibit its enzymatic activity, while PKCζ deletion restores the necessary metabolic processes mediated through the SSP in starved cancer cells." (PMID 36755301, 2023). "We then asked why PHGDH inhibition cannot be compensated for with exogenous serine, one possible explanation is the relatively low-baseline mRNA expression of the serine transporter SLC1A5 in OS cells, as shown in data from the Cancer Cell Line Encyclopedia." (PMID 35186770, 2022). "Furthermore, RNF5 was able to degrade phosphoglycerate dehydrogenase (PHGDH), the first enzyme of the serine synthesis pathway, which is significantly upregulated in many cancers." (PMID 35406574, 2022). "Based on initial reports on the importance of PHGDH in cancer cells, PHGDH inhibition does not decrease intracellular serine levels." (PMID 36319669, 2022). "The WGCNA on DEFs of paired NSCLCs revealed association of low tumour folate with increased transcripts of GLUT1/4, PHGDH, PSPH, and PSAT1 in NSCLCs, suggesting increased glucose uptake and enhanced glycolytic SSP pathways to contribute cancer serine levels under folate-deficit condition." (PMID 36615660, 2022). "Here, we provide the first evidence that circ_0062682 activates the serine synthesis pathway by regulating the miR-940/PHGDH axis, thereby increasing NADPH and GSH levels and reducing ROS levels in CRC cells to promote the survival of cancer cells under stress conditions." (PMID 34957102, 2021). "Additionally, D-2-HG can be produced by the promiscuous activity of phosphoglycerate dehydrogenase (PHGDH), an enzyme frequently overexpressed in cancer." (PMID 31900386, 2020). "And some recent researches reported that PHGDH promoted some tumors growth via non-metabolic way by upregulating target cancer-promoting genes." (PMID 32226297, 2020). "Hence, certain key proteins involved in this disruptive metabolism, such as GLUT, hexokinase-2 (HK2) and phosphoglycerate dehydrogenase (PHGDH), which are overexpressed in cancer, have been examined as possible targets." (PMID 33330106, 2020). "Importantly, in these mouse xenograft cancer model studies, control tumors contain low levels of FOXO4 and COP1 while demonstrate relatively high levels of PHGDH and Glut1." (PMID 33101846, 2020). "Despite reports that suppression of PHGDH can impair cancer cell proliferation, we find that PHGDH deletion does not attenuate cell proliferation in PDAC cells." (PMID 31893043, 2019). "We chose these enzymes for experimental validation, as well as three other enzymes that have been investigated in recent cancer studies, namely ribose-5-phosphate isomerase (RPI), phosphoglycerate dehydrogenase (PHGDH) and phosphoserine transaminase (PSAT) as positive controls." (PMID 31601242, 2019). "The PHGDH promoter is positively regulated by specificity protein 1 (SP1) and nuclear transcription factor Y (NFY), two transcription factors that are often upregulated in cancer." (PMID 29740540, 2018).
cancer (continued). "Assuming that PHGDH expression indicates cell-autonomous serine synthesis, then cell-autonomous serine synthesis is not uniformly required for cancer cell proliferation in 2D monolayer cultures in complete growth medium." (PMID 29925909, 2018). "Therefore, we analyzed the relationship between the co-expression of PHGDH and Oct4 or SOX9, and the clinical outcome from cancer." (PMID 30250195, 2018). "PHGDH, a rate-limiting enzyme of the serine biosynthesis pathway, also uses NAD as a co-enzyme, and the intracellular level of NAD is considered to be an important regulator for serine biosynthesis in cancer cells." (PMID 30631755, 2018). "Analysis of PHGDH levels in different cancer cell lines revealed upregulation of PHGDH mRNA rather than changes in enzymatic activity to be the reason for elevated PHGDH activity in human tumour cells." (PMID 29568346, 2018). "Altogether these findings, showing that PHGDH deficiency promotes autophagy (not apoptosis), sheds more light on PHGDH-related growth mechanisms in cancer stem-like cells." (PMID 30250195, 2018). "Both compounds were shown to inhibit PHGDH activity in a non-competitive manner and to selectively target cancer cell lines dependent on de novo serine synthesis." (PMID 29568346, 2018). "Thus, PHGDH overexpression and consequent increased NADPH production from the mitochondrial folate cycle are important mechanisms determining cancer stem cell maintenance under oxidative stress." (PMID 28649560, 2017). "PSAT1, PHGDH, and SHMT2 are three key enzymes in the serine and glycine pathway and enhanced serine and glycine biosynthesis provides sufficient precursors for the synthesis of proteins, nucleic acids, and lipids for highly proliferating cancer cells." (PMID 28693523, 2017). "Then, lacking an alternative explanation, they concluded that, perhaps, serine production is not the only important role for PHGDH in cancer cells." (PMID 25574168, 2014). "Their study suggested that serine production from the glycolytic intermediate mediated by PHGDH/PSAT1/PSPH pathway is unlike to be the reason of the cancer dependency of PHGDH in vitro." (PMID 24318446, 2013). "Considering what was yet unknown in the current literature on cancer cell metabolism we investigated two genes whose expression was HER2 oncogene-regulated, VAMP8 and PHGDH, for their roles in HER2 oncogene-driven insulin-independence." (PMID 21437235, 2011). "Besides, by evaluating the expression levels of cancer stem cell (CSC) surface markers, EpCAM, CD24, CD133 and CD44 by flow cytometry, we confirmed a direct correlation between stemness markers levels and PHGDH expression in HCT8 and RKO P1 colonspheres." (PMID 40640948, 2025). "Consequently, inhibited PHGDH combined with suppressed pyruvate kinase (PK) M2 can inhibit cancer cell proliferation and induce G2/M phase arrest in non-small cell lung cancer A549 cells." (PMID 40078876, 2025). "Moreover, 70% of estrogen receptor-negative breast tumors exhibit elevated PHGDH protein levels, and its inhibition reduces cancer cell survival." (PMID 40723225, 2025). "In keeping, more recent studies have guessed different non-metabolic roles of PHGDH in cancer." (PMID 40640948, 2025). "The expression of another TAM marker, vascular endothelial growth factor (VEGF; also called VEGF-A), was also reduced by PHGDH deficiency, suggesting that PHGDH plays a crucial role in promoting M2-like TEM polarization, regardless of the PHGDH levels in the corresponding cancer cells." (PMID 38409249, 2024). "Specific PHGDH inhibitors that do not affect cancer growth in the standard medium may still be effective in slowing cancer growth in vivo, in part because of their systemic rather than local anti-cancer activity." (PMID 37664062, 2023).